IL6 (interleukin 6)
Diseases named in the same sentence as IL6 in open-access papers (continued):
Sharing a sentence is not in itself a finding about the gene and the disease.
tumor (continued). "Inflammatory cytokines, such as interleukin-6 (IL-6) and tumor necrosis factor-alpha (TNF-α), are elevated during COVID-19 infection and can create an environment conducive to tumor growth and metastasis." (PMID 39156288, 2024). "Serum IL-6 concentration is elevated in patients with CCA compared to healthy controls and is positively correlated with tumor burden." (PMID 38881895, 2024). "Inflammatory cytokines like interleukin-1 and interleukin-6, which act on the liver to produce hs-CRP, can be produced by inflammatory cells in the tumor microenvironment." (PMID 38384810, 2024). "IL-6 activates Signal Transducer and Activator of Transcription 3 (STAT3), thereby facilitating tumor initiation and growth." (PMID 39683442, 2024). "During tumor progression, the proliferation and invasion of tumor cells as well as the EMT process are controlled by TME-mediated secretion of several growth factors and cytokines including TGF-β, IL-6, IL-8, IL-10 and VEGF." (PMID 39335188, 2024). "Among the components of the tumor immune microenvironment, the degrees of CD4 + cell and CD163 + cell infiltration and IL-6 expression in cancer tissues were significantly correlated with FDG PET/CT imaging features of primary tumors." (PMID 38627864, 2024). "Patients with severe CD163 + macrophage infiltration and increased IL-6 expression showed increased FDG uptake, metabolic volumetric parameters, and metabolic heterogeneity of tumor lesions, as well as increased FDG uptake in the BM and spleen." (PMID 38627864, 2024). "Typically, M1 macrophages are induced by LPS and IFN-γ, and they produce pro-inflammatory cytokines, including IL-6, TNF-α, and IL-1β, which possess potent anti-tumor effects." (PMID 39795180, 2024). "Immunohistochemical analysis showed that the expression levels of IL-6, IL-6R, and STAT3 in tumor tissue of mice treated with ginsenoside Rh2 were inhibited." (PMID 39845783, 2024). "The results revealed that the expression of IL-6 was lower, while the expression of STAT3 was higher in tumor tissues compared to normal tissues." (PMID 38881895, 2024). "Differential gene expression results revealed five genes (IDO1, IL6, TNF, CD209, and FOXP3) that were, on average, upregulated ≥ 2-fold or downregulated ≤ –2-fold in treated tumor regions relative to untreated tumor regions." (PMID 39335552, 2024). "The aberrant production of IL-6 is the result of TME chronic inflammation, so tumor cells will produce and secrete more endogenous IL-6 when proliferating, infiltrating, or metastasizing." (PMID 39372416, 2024). "M1 macrophages can enhance the ability of CD8 + T cells and NK cells to emit tumor cells or induce tumor cell apoptosis by secreting TNF, IL-6, IL-12, and other cytokines." (PMID 38713256, 2024). "Residual tumour cells post NACT were enhanced for several relevant pathways including DNA damage, Apoptosis, IL6-Jak-Stat3, Hedgehog, Wnt beta catenin signalling, and inflammatory response whilst a mitosis gene set was reduced." (PMID 39341888, 2024). "Studies have shown that tumor-infiltrating monocytes, macrophages, and neutrophils secrete large amounts of pro-inflammatory cytokines such as IL-6, IL-8, and TNF-α, promoting tumor development in CAC models." (PMID 38516408, 2024). "IL-6 and IFN-γ were reported to regulate the expression of PD-1 and PD-L1 in the tumor microenvironment." (PMID 38404585, 2024). "In general, protein kinases PKA-Cα and AMPK-α1 play a critical role in regulating the IL-6/STAT3 signaling pathway and the growth and apoptosis of tumor cells." (PMID 39845783, 2024). "Based on this, we assessed the therapeutic efficacy of double blockade of IL6 and CCR2 signaling in orthotopic tumor models." (PMID 38468260, 2024). "Our study also provided evidence that the IL6/IL6R and CCL2/CCR2 signaling pathways within the TME exert a greater influence on the ability of HPV − tumor cells to evade immune attack by NK cells compared to HPV + tumors." (PMID 38468260, 2024).
tumor (continued). "The tumor treated with P-E/S Lip expressed higher protein levels of TNF-α and IL-6 compared with the control tumors." (PMID 39068444, 2024). "In inflammatory or tumor environments, inflammatory cytokines such as IFN-γ, IL-6, and TNF-α can increase the activity of indoleamine 2,3-dioxygenase (IDO)." (PMID 39156806, 2024). "CRC-regulated macrophages regulate the EMT program and enhance migration and infiltration of CRC cells by secreting IL6, which activates the JAK2/STAT3 pathway and suppresses the tumor suppressor miR-506-3p in CRC cells." (PMID 39068459, 2024). "For example, both IL-6 and CXCL8 are reported to be elevated in KRAS-driven STK11-null LUADs and proposed to promote tumor immune evasion." (PMID 37968341, 2024). "As expected, dual IL6 and CCR2 blockade reduced the tumor burden in an orthotopic mouse model of HPV − tumors more efficiently than either agent alone." (PMID 38468260, 2024). "Activated YAP1 upregulates the secretion of IL-6 and TNF-α from tumor cells, as well as colony-stimulating factor 1-3 (CSF1-3), CXC motif chemokine ligand 5(CXCL5), PGE2, COX2, and other factors that recruit MDSCs." (PMID 38550587, 2024). "The selection of cytokines was based on their significant role in regulating the tumor microenvironment, including promoting either the Th1 (IL-2RA, IL-12(p40), IL-15, TNF-α, IL-1β, IL-1RA, and IFN-γ) or the Th2 (IL-4, IL-6, IL-8, and IL-10) profile." (PMID 39768997, 2024). "Some inflammatory mediators or cytokines, such as interleukin-6 (IL-6) and tumor necrosis factor-alpha (TNF-α), can promote tumor growth and metastasis." (PMID 38731833, 2024). "In BC, Gr1+CD11b+ cells, educated by the tumor, secrete OSM and IL6, significantly expanding the metastatic SCA1+ cell population within the cancer." (PMID 39286635, 2024). "Given the right stimuli, IL-6 secretion can be induced in immune and stromal cells, but cultured MPE tumor cells secrete it constitutively." (PMID 39114667, 2024). "The findings demonstrate that cancer cell-secreted IL-6 and PDGF in the tumour milieu are necessary to stimulate MSC migration into the head and neck tumour niche." (PMID 39120301, 2024). "Cytokines secreted by MSCs, such as IL-6 (interleukin-6), bFGF (basic fibroblast growth factor), and PGE2, drive/accelerate tumor cell growth." (PMID 38674102, 2024). "Pro-inflammatory cytokines like IL-6 and TNF-α can promote tumor cell proliferation and survival, while anti-inflammatory cytokines such as IL-10 contribute to immune evasion." (PMID 39200315, 2024). "The innate immune response was further amplified by the increase in the levels of pro-inflammatory factors, such as IL-6 in serum and TNF-α in tumor tissues." (PMID 39010088, 2024). "The production of IL-6 through this pathway activates the STAT3 pathway in tumor cells, thereby promoting tumor survival and growth." (PMID 38523155, 2024). "In the TME, IL-6 can bind its receptor, transmit signals through the downstream JAK/STAT3 pathway, and activate the transcription of tumor-related genes." (PMID 39372416, 2024). "Despite this, there was evidence of anti‐tumor activity such as the low number of CD163+ cells, greater necrosis, high levels of IL‐10 and low levels of IL‐6 and IL‐27." (PMID 38600057, 2024). "Compared with the tumor group, CUMS significantly decreased HDC and HIS levels and increased IL-6, IL-17A, NE, COR, and 5-HT levels." (PMID 39720595, 2024). "M-CSF induces regulatory macrophages for homeostasis, and GM-CSF generates inflammatory macrophages, secreting IL-6, IL-1β, and TNF-α, with IFN-γ enhancing this production, potentially aiding tumor growth." (PMID 38713256, 2024). "Nonetheless, factors like IL-6, TGF-β, and IL-10, secreted by tumor cells, perpetuate chronic inflammation, stimulating immunosuppressive myeloid-derived suppressor cells, macrophages, and neutrophils." (PMID 39664377, 2024).
tumor (continued). "Mediators derived from cancer cells and their surrounding stromal cells, such as IL-6, PGE2, TGF-β, hyaluronic acid fragments (HA), and G-CSF/GM-CSF, contribute to the reprogramming of neutrophils into a tumor-promoting phenotype." (PMID 38760815, 2024). "Our findings align with recent studies indicating the crucial role of the IL-6/JAK/STAT3 signaling axis in cancer progression, particularly in influencing the tumor immune microenvironment." (PMID 38429845, 2024). "Elevated levels of IL-6, phosphorylated JAK2, and phosphorylated STAT3 are consistently observed across these malignancies, contributing to tumor growth, metastasis, and resistance to apoptosis." (PMID 39125732, 2024). "Corresponding to the observations here, conversion of slowly cycling tumor cells in culture to a highly proliferative and invasive phenotype requires the stromal synthesis of both CSF3 and IL-6." (PMID 39338937, 2024). "Elevated serum levels of IL-6 in metastatic and castration-resistant prostate cancer (CRPC) patients correlate significantly with tumor staging and negatively with survival and treatment response." (PMID 39355131, 2024). "This response promotes the release of immunosuppressive cytokines (IL-4, IL-10) and elevates pro-inflammatory markers, like IL-6 and VEGF, creating a tumor-supporting microenvironment." (PMID 39766169, 2024). "IL-6 was reported to skew T-cell differentiation toward Th2 by STAT3 signaling pathway, resulting in the suppression of anti-tumor response." (PMID 39963655, 2024). "What is more, HPV increases the expression of IL‐6, IL‐8, and TGF‐β, enhancing tumor cell proliferation, migration, and invasion." (PMID 39170944, 2024). "Studies have shown that reducing TNF-α and IL-6 levels and increasing IFN-γ can help inhibit inflammation and tumor cell proliferation." (PMID 39508039, 2024). "Our study reveals a role of the circRNA-induced fibroblast niche in tumor metastasis and highlights that targeting the circNOX4/FAP/IL-6 axis is a promising strategy for the intervention of NSCLC metastasis." (PMID 38459511, 2024). "For instance, experimental studies have shown that sleep deprivation in animal models leads to increased levels of pro-inflammatory cytokines like IL-6 and TNF-α, which can suppress immune surveillance and promote tumor growth." (PMID 39120277, 2024). "We established an IFP based on three inflammatory biomarkers (IL6, osteocalcin, SII) and a tumor marker AFP." (PMID 39188937, 2024). "It releases a variety of cytokines, chemokines, and growth factors that promote tumour cell survival and proliferation, such as prostaglandin E2 (PGE2), CCL17, interleukin-6 (IL-6), tumour necrosis factor-alpha (TNF-α), VEGF, and epidermal growth factor (EGF)." (PMID 38218739, 2024). "Myeloid-derived suppressor cells (MDSCs), another source of IL6 in the TME, support immune suppression by inhibiting T cell function, allowing tumor cells to evade immune responses and increase tumor growth." (PMID 39766086, 2024). "IL-6 is an important cytokine in LCA that promotes epithelial-mesenchymal transition and tumor metastasis, facilitating the migration and invasion of LCA cells." (PMID 38903721, 2024). "recently demonstrated that the simultaneous blockade of IL-6 and C-C motif chemokine receptor 2 (CCR2) enhanced the anti-tumor activity of NK cells in HNSCC." (PMID 39411143, 2024). "In the current study, we evaluated the regulation of ST6GAL1 by two pro-inflammatory cytokines, IL-1β and IL-6, which are abundant within the PDAC tumor microenvironment." (PMID 39260693, 2024).
tumor (continued). "IFN-γ is a cellular interferon that can regulate immune function and inhibit tumor cell proliferation, TNF-α is related to inflammatory response and immune response, and IL-6 is the most central inflammatory factor that links inflammation and tumors." (PMID 39508039, 2024). "B1R also contributes to the pro-tumor chemokines and cytokines secretion, like CCL5, IL-6, CXCL11, and IL-8, in GBM, promoting MON infiltration into the TME." (PMID 38720342, 2024). "Regional anesthesia also lowers IL-6 and VEGF levels, preventing the formation of a pro-tumor environment." (PMID 39766169, 2024). "We found IL6, and IL11 expression was significantly upregulated in patients with primary tumours (n = 1450), as well as in patients with metastatic lesions (n = 99) when compared to expression levels in the normal colon of patients (n = 377)." (PMID 38600086, 2024). "IL-6 is an important mediator of cross-talk between CAF and tumor cell, CAF derived IL-6 can regulate immune response, drug resistance and tumor metastasis in multiple cancers." (PMID 38311608, 2024). "This polarization results in increased secretion of IL-6, IL-8, and TNF-α, impacting tumor resistance, growth, angiogenesis, and other facets of tumor progression." (PMID 39578849, 2024). "It has also been reported that p38 inhibition decreases the expression of IL-6 and VGEF by BM stromal cells, resulting in the inhibition of MM cell proliferation and adhesion, thus decreasing the tumor burden and angiogenesis in murine models of MM." (PMID 38254747, 2024). "Tumor-derived factors such as VEGF, IL-6, and IL-10 recruit MDSCs which in turn produce more VEGF via STAT3 signaling, thereby establishing a positive feedback loop that potentiates tumor angiogenesis." (PMID 38520006, 2024). "Among them, angiogenesis, IL6-JAK-STAT3, IL2/STAT5, complement system, interferon gamma response, and G2M checkpoint, are crucial for tumour growth, inflammation, and immune system evasion." (PMID 39107713, 2024). "The induction of IL-6 and CSF3 in MHV68-infected K-RasLA1 mice implicates tumor promotion mediated by MDSC recruitment." (PMID 39338937, 2024). "In tumor tissues, there was a moderate correlation between IL-6 and STAT3 (r = 0.449, P < 0.001), whereas a weak correction between IL-6 and gp130 (r= 0.314, P = 0.002), as well as JAK2 (r = 0.230, P = 0.028)." (PMID 38881895, 2024). "Tumor cells promote fibrosis by persistently releasing inflammatory factors like IL-1, TGF-β1, TNF, and IL-6, which activate the NF-κB and JAK/STAT signaling pathways, inducing fibroblast differentiation into a pro-inflammatory phenotype or myofibroblasts." (PMID 39534084, 2024). "Other than immune-modulating cytokines such as IL-10, IL-17, IL-23, and TGF-β (assisting tumor growth), IFN-γ, TNF-α, GM-CSF, IL-2, IL-6, IL-17, and IL-1 stimulate immune surveillance and prevent tum development." (PMID 38951583, 2024). "This process is facilitated by bacterial translocation from the primary tumor site, which recruits neutrophils via cytokines such as IL-1β, CCL2, TNF-α, and IL-6, thereby establishing a pre-metastatic niche in the liver." (PMID 39795864, 2024). "With intracytoplasmic DNA, cGAS-STING agonist can increase the production of interleukin 6 (IL-6), tumor necrosis factor (TNF) and interferon (IFN) and play a regulatory role in inflammation and tumor treatment." (PMID 39125107, 2024). "IL-6, an inflammatory factor, is another key cytokine released by CAFs that promotes EMT in tumor cells." (PMID 38244071, 2024). "Our findings also suggest that levels of the IL-6 gene are significantly lower in both AC and SCC tumor tissues than in para-tumor tissues." (PMID 38103126, 2024). "It has been observed that CAFs can directly secrete IL-6, and IL-8 stimulates STAT3/Notch signaling pathways to sustain the stemness of tumor cells." (PMID 39578849, 2024).
tumor (continued). "In Pten‐null senescent tumours, the JAK2/STAT3 pathway was activated, resulting in the secretion of CXCL1, CXCL2 and IL‐6, thereby promoting macrophage M2 polarisation." (PMID 39270064, 2024). "Of the immune cells, TAMs are the most abundant and produce a variety of proinflammatory cytokines in the TME, such as IL‐6 and TNF‐α, and promote tumour cell growth." (PMID 37974543, 2024). "IL-6 derived from RAW264.7 further enhanced the metastatic properties of 4T1 cells in vitro and promoted tumor progression in vivo by inducing stem cell-related transcription factor expression through the STAT-3 pathway." (PMID 38355711, 2024). "They observed that signaling molecules released by tumor cells, such as reactive oxygen species (ROS), PDGF, and IL-6, have the potential to alter the metabolism, characteristics, and secretory profile of fibroblasts, causing them to transit to CAF phenotypes." (PMID 38562556, 2024). "This imbalance affects tumor progression and invasive behaviors such as tumor metastasis, and the TGF-β/IL-2 and IL-6 cytokine axes greatly contribute to Th17/Treg homeostasis." (PMID 39534095, 2024). "Key cytokines such as TNF, IL-1, IL-6, IL-12, IL-18 (stimulatory), and TGF-β, IL-4, and IL-10 (inhibitory) mediate interactions between these cells, creating a network that facilitates tumor growth and immune evasion." (PMID 39449800, 2024). "BMAs secrete adipocytokines such as leptin, adiponectin, IL-1β, IL-6, VCAM-1, TNF-α, and VEGF to promote tumor cell metastasis." (PMID 38770000, 2024). "Notably, novel biomarkers beyond overexpression of STAT3 pY705 may provide a more comprehensive approach to guiding STAT3-directed treatments and may include upstream ligands such as IL-6 that could be serially monitored with the convenience of a blood test compared to serial tumor biopsies." (PMID 38339245, 2024). "IL-6 and TNF-α were chosen as inflammatory indicators to evaluate the changes in the tumor microenvironment." (PMID 39065602, 2024). "PI3K/Akt pathway was suggested to coordinate the upregulation of cytokines, such as IL6 and IL7 in tumor microenvironment during HCC recurrence." (PMID 38840185, 2024). "Fibroblast clones secrete IL-6, IL-8, NFkB, IFN-y, HGF, CTGF, CCL5, and PGE5 to promote tumour growth." (PMID 39046819, 2024). "IL-6 and IL-8 are cytokines released by RCC that contribute to tumor progression, angiogenesis, and the maintenance of an inflammatory microenvironment." (PMID 38653823, 2024). "Verteporfin, the inhibitor of YAP1, downregulated IL-6, CSF1-3, and CXCL5, which compel MDSCs in tumor." (PMID 38550587, 2024). "As previously reported, Probio-M9 substantially reduced the inflammatory response, infiltration of CD68+ macrophages in the non-tumor area, expression of TNF-α and IL-6, and number of Ki67-positive proliferating cells in the tumor area." (PMID 38540144, 2024). "In lung adenocarcinoma, EGFR mutations are prevalent and are often associated with increased levels of inflammatory cytokines like IL-6 and TNF-α, which contribute to tumor progression." (PMID 39990858, 2024). "Proinflammatory cytokines such as IL-6, IL-1α, IL-1β and IL1RA are primarily secreted by activated myeloid cells and play critical roles in an anti-tumor immune response." (PMID 38400933, 2024). "TAM-derived IL-6 activated the JAK2/STAT3 pathway, and activated STAT3 inhibited transcription of the tumor suppressor miR-506-3p in CRC cells." (PMID 39199574, 2024). "For instance, they release cytokines like IL-6 and TNF-α, or vascular endothelial growth factor (VEGF) and matrix metalloproteinases (MMP) that have been involved in cancer cell proliferation and tumor metastasis." (PMID 39256468, 2024). "Our results showed that astragaloside IV-PESV was able to inhibit tumor growth by inhibiting NF-κB, TNF-α and IL-6." (PMID 38622523, 2024).